CAV1 (caveolin 1)
Diseases named in the same sentence as CAV1 in open-access papers (continued):
Sharing a sentence is not in itself a finding about the gene and the disease.
breast carcinoma (continued). "Also caveolin-1 tyrosine phosphorylation was recently shown to sensitize MCF7 breast cancer cells to paclitaxel-induced apoptosis by inactivating Bcl2 and increasing mitochondrial permeability." (PMID 18400052, 2008). "Likewise, caveolin-1 expression is increased in multi-drug resistant MCF7 breast cancer cells and caveolin-1 expression in these cells promotes anchorage-independent survival by preventing anoikis." (PMID 18400052, 2008). "For instance, absence of caveolin-1 expression in primary mammary tumours and tumour-derived cell lines was linked to absence of the protein in primary ductal epithelial cells rather than suppression of expression via promotor methylation." (PMID 18400052, 2008). "Furthermore, Caveolin-1 has been demonstrated to mediate medroxyprogesterone acetate-(MPA)-induced breast cancer cell growth." (PMID 17915016, 2007). "Our findings suggest that caveolin-1 may still possess tumor suppressor activities in basal-like breast cancers." (PMID 17764562, 2007). "Since inhibitors of Caveolin-1 signalling are available, targeting Caveolin-1 in breast cancer may represent a potential option for future breast cancer treatment." (PMID 17915016, 2007). "CDIM9 induced increases in tumor caveolin-1 and p27 in vivo, which may contribute to its antitumor activity in basal-like breast cancer." (PMID 17764562, 2007). "Thus, the role of Caveolin-1 in breast cancer tumourigenesis and progression still remains ill-defined." (PMID 17915016, 2007). "Increased caveolin-1 expression was also detected in breast carcinoma tissue samples." (PMID 18949068, 2007). "Caveolin-1 and -2 (CAV1, CAV2) are closely linked genes localised to the fragile region of 7q31 (FRA7G), and loss of heterozygosity involving this region has been reported in breast cancer." (PMID 15305200, 2004). "Furthermore, re-expression of caveolin-1 inhibited the growth of breast carcinoma cells and colony formation of sarcoma cells and ectopic caveolin-1 expression reduced tumorigenecity of colon carcinoma cells." (PMID 11953823, 2002). "Thus far, a decreased expression of caveolin-1 has been found in a variety of cell lines such as those of breast carcinoma, lung carcinoma, sarcoma, uterine cervical carcinoma, and colon carcinoma." (PMID 11953823, 2002). "However, some studies have found that in breast cancer, the regulatory relationship between Cav-1 and autophagy may be positive." (PMID 41030451, 2025). "Moreover, targeting S100 exosomes with monoclonal antibodies against CAV1 may offer improved outcomes, as demonstrated in preliminary breast cancer studies." (PMID 39893499, 2025). "Supporting this hypothesis, breast cancer cells co-expressing Cav-1 and cathepsin B exhibit higher malignancy than other cells owing to their increased invasion and metastasis, which is likely attributed to increased secretion of cathepsin B and subsequent extracellular matrix degradation." (PMID 40135201, 2025). "Consequently, opinions about whether Cav-1 is an oncogenic gene or a tumor suppressor in breast cancer are divided." (PMID 40579643, 2025). "Therefore, we performed data mining in the few publicly available data sets that are available and have stromal data and found that Cav1 mRNA levels were lower in black (AA) women with breast cancer when compared to white (CA) women in Oncomine (Chang dataset, Oncomine)." (PMID 37822942, 2023). "Although there are multiple studies that have demonstrated the role of miRNAs in breast cancer and both their diagnostic and prognostic value, there are few linking the expression of a miRNA-mediated mechanism of Cav1 loss and none that address the loss of Cav1 in the stromal compartment." (PMID 37822942, 2023).
breast carcinoma (continued). "Resistance-associated proteins were Caveolin-1, PgR, mTOR, phosphorylated MEK1/2 (pSer217/221) of the Erk/MAPK signaling pathway, phosphorylated IKKα (pThr23) of the NFκB pathway, the microtubule-associated protein Tau and the basal breast cancer markers CK5, CK6 and Vimentin-pSer56." (PMID 37596623, 2023). "Therefore, Cav-1 may play an important role in the invasion and metastasis of breast cancer by regulating epithelial-mesenchymal transformation, extracellular matrix changes, Rho family proteins and integrin endocytosis." (PMID 37828916, 2023). "Interestingly, Cav-1 plays an important role in these processes and can affect the migration and invasion of breast cancer cells by regulating the expression of epithelial mesenchymal transition (EMT)-related markers, matrix metalloproteinases (MMPs) and Rho-GTPases." (PMID 37828916, 2023). "In addition, CAV-1 deficiency in fibroblasts increases the secretion of TGF-β, which in turn activates the TGF-β/Smad signal pathway in breast cancer, thus, promoting the metastasis and dryness of breast cancer tumors." (PMID 37978384, 2023). "Thus, the CAV-1 expression level in breast cancer tissues might be a predictive biomarker for breast cancer." (PMID 36604141, 2022). "Caveolin-1, Desmin, microfibril associated glycoprotein 4, fibrillin 1 and collagenα-1 have been identified as potential biomarkers that can discriminate metastatic from non-metastatic sentinel lymph nodes in early breast cancer." (PMID 35599267, 2022). "Notably, miR-203 and Caveolin 1 (CAV1) have also been found to play a role in breast cancer." (PMID 36233075, 2022). "Therefore, the expression level of CAV-1 may serve as an intrinsic biomarker for the sensitivity of HER2-positive breast cancer cells to T-DM1." (PMID 36210846, 2022). "Another study confirmed the absence of CAV1 gene mutations in human breast cancer." (PMID 36233075, 2022). "However, CAV1 knockout was insufficient to resensitize HER2-positive breast cancer cells to T-DM1." (PMID 36210846, 2022). "In addition, the IHC and WB results of collected breast cancer tissues indicated that tumor-stromal CAV-1 expression is reduced, while the EMT and stemness of BCCs were activated, in cancer tissues with lymph node metastasis, but the exact mechanism remains ambiguous." (PMID 36604141, 2022). "Notably, in recent studies, the dual role of CAV1 is evident in breast cancer progression." (PMID 36233075, 2022). "Previous studies have shown that PM chol appropriate levels in human melanoma cells and caveolin-1 in breast cancer cells regulate the formation and function of invadopodia and that disruption of lipid rafts by mβCD suppresses invadopodia formation and breast cancer cell invasion." (PMID 35819726, 2022). "Clinical retrospective studies on breast cancer patients focusing on the expression of caveolin-1, which acts as a tumor-suppressing molecule in CAFs, showed 72 months of cancer-specific survival in caveolin-1-positive patients, whereas only 29.5 months in caveolin-1-negative patients." (PMID 36230508, 2022). "In another study, the analysis of human breast cancer datasets revealed that the expression of caveolin-1 (CAV-1) was inversely correlated to that of NRF2 or superoxide dismutase-2 (SOD-2), and this could predict the development of more aggressive forms of cancer." (PMID 33805996, 2021). "Additionally, Cav-1 exhibited decreased expression in breast cancer cells than normal breast epithelial cells, and its overexpression could inhibit the glycolytic metabolism of breast cancer." (PMID 34568078, 2021). "The high levels of CAV1 may serve as a prognostic biomarker for patients with breast cancer." (PMID 34234869, 2021).
breast carcinoma (continued). "Another potential candidate is CAV1 (caveolin-1), located at 7q31, which can act either as an oncogene (as described in bladder, thyroid, and esophageal cancers) or as a tumor suppressor gene (in ovarian, lung, and mammary tumors), depending on the tissue type or the microenvironmental influence." (PMID 34590593, 2021). "Indeed, downregulation of CAV1 promotes autophagy along with lysosome function by membrane raft disruption in breast cancer cell lines and in tumor-compromised tissue, suggesting that CAV1 may inhibit breast cancer development by modulating autophagy." (PMID 32458269, 2020). "For example, Cav-1 reconstitution could suppress aerobic glycolysis in breast cancer cells." (PMID 32528105, 2020). "Intriguingly, Cav-1 silencing not only suppressed the migratory-stimulating effect of hypoxia but also enhanced the ability of SA in suppressing metastasis, indicating that Cav-1 may act as the main pharmaceutical target of SA in suppressing breast cancer metastasis under hypoxic stress." (PMID 33381039, 2020). "Therefore, in our next study, we plan to investigate whether Cav-1 transcription can be directly regulated by Hif-1α in human breast cancer, and whether SA can interrupt this interaction." (PMID 33381039, 2020). "Therefore, a Cav-1-resurrection strategy in BCSCs may be a potential treatment strategy for breast cancer." (PMID 32528105, 2020). "Additionally, multivariate Cox regression analysis showed that a low expression level of epithelial Cav-1 was an independent hazard for overall survival in breast cancer patients (P = 0.002), strongly suggesting epithelial Cav-1 as a potential prognostic marker for breast cancer." (PMID 32528105, 2020). "In both mouse breast cancer xenograft and zebrafish xenotransplantation models, SA inhibited breast cancer growth and inhibited late-phase autophagy in vivo, which was accompanied by suppression of Hif-1α/Cav-1 signaling and the epithelial-mesenchymal transition." (PMID 33381039, 2020). "Moreover, by co-implanting caveolin-1-expressing or caveolin-1-deficient fibroblasts with breast cancer cells in nude mice, they confirmed that the expression of caveolin-1 does not affect the tumor growth at the implantation site." (PMID 31845646, 2019). "Along a different line, a recent study with the herbal adjuvant drug termed Oldenlandia diffusa (OD), which is used in traditional Chinese medicine to treat advanced-stage breast cancer patients, may inhibit the development of metastasis by diminishing CAV1 expression." (PMID 31362353, 2019). "Thus, in the context of mammary gland development, the increase of cav-1 expressed in the fat-1 mouse may have protective effects against mammary tumour growth later in life." (PMID 31619022, 2019). "Interestingly, our study demonstrated that ADQ could inhibit CAV1 to improve breast cancer chemosensitivity." (PMID 30333750, 2018). "Therefore, whether metformin-mediated caveolin-1 overexpression can improve T-DM1 efficacy in breast cancer cells was examined in this study." (PMID 29500444, 2018). "Enrichment analysis and experimental validation demonstrated that ADQ might improve breast cancer chemosensitivity via inhibiting caveolin-1, which further triggered expression changes of cell cycle-related proteins p21/cyclinB1 and apoptosis-associated proteins PARP1, BAX and Bcl-2." (PMID 30333750, 2018). "Furthermore, whether expression of caveolin-1 could be induced by treatment with trastuzumab or taxanes in breast cancer cells to obtain a greater beneficial effect of T-DM1 treatment was also assessed in the current study." (PMID 29500444, 2018). "Regardless, additional validation of tumor/stromal Cav-1 in breast cancer patients as a predictive biomarker for nab-paclitaxel therapy is warranted, and tumor/stromal Cav-1 of metastatic sites through re-biopsy may better reflect the efficacy of nab-paclitaxel in metastatic breast cancer patients." (PMID 30348118, 2018).
breast carcinoma (continued). "Importantly, the observed angiogenic phenotype was consistent in our spontaneous breast cancer model and was organ specific, because PyMT lung metastases in Cav1 KO→WT chimeric mice showed increased blood vessel density, whereas experimental liver metastases did not." (PMID 29212030, 2017). "Additionally, it was reported that CAV1 silencing could sensitize breast cancer stem cells (CSCs) by limiting their self-renewal ability but promoting the differentiation process." (PMID 28546853, 2017). "Based on the results reported here, we postulate that the levels of Cav-1 and MnSOD expression are determinant to metabolic changes that support tumor progression and that the Cav-1low/MnSODhigh phenotype indicates a subgroup of aggressive types of breast cancer with poorer prognosis." (PMID 26543228, 2016). "However, caveolin-1 may participate in different signaling pathways depending on cell type and the genetic background of the breast cancer." (PMID 26172389, 2015). "Thus, caveolin-1 protein may be an effective predictor for determining the outcome of T-DM1 treatment in breast cancer patients." (PMID 26172389, 2015). "Therefore it may suggest that different breast cancer subtypes may have different changes in epigenetic regulation of CAV1." (PMID 26112043, 2015). "Furthermore, CAV1 expression in the CAFs of breast cancer correlated with low survival." (PMID 25633184, 2015). "As an example, orthotopical implantation of mammary tumor cells in caveolin (Cav)-1 knockout mice, a model of accelerated host aging, had increased stromal content relative to those cells implanted into control microenvironments [Cav-1(+/+) versus Cav-1(−/−) age-matched young female mice]." (PMID 26284191, 2015). "In addition, genetic knockout of caveolin-1 results in mammary gland ductal epithelial cell hyperplasia and accelerates mammary tumorigenesis and lung metastases in mice that is prone to develop breast cancer." (PMID 25397596, 2014). "Because our data have shown that caveolin-1 inhibition in MCF-7 breast cancer lines promote cell proliferation and invasion via activation and up-regulation surface expression of BKCa channels, we next investigated whether enforced caveolin-1 expression may lead to opposite effects." (PMID 25397596, 2014). "Furthermore, differential methylation of CGI shores, but not CGIs, significantly regulated CAV1 expression, and breast cancer aggressiveness was associated with CAV1 CGI shore methylation levels." (PMID 23887935, 2013). "Similarly, mammary tumor samples derived from caveolin-1 knockouts crossed with mouse mammary tumor virus-polyoma middle T antigen [PyMT/Cav-1(-/-)] mice show ERK-1/2 hyperactivation, cyclin D1 up-regulation, and Rb hyperphosphorylation, consistent with dysregulated cell proliferation." (PMID 24236206, 2013). "Our model indicates that mammary tumor cells with epithelial characteristics lack caveolin-1 while mesenchymal tumor cells express caveolin-1 suggesting that caveolin-1 may serve as a marker of mammary tumor cells with mesenchymal characteristics such as claudin-low breast tumors." (PMID 22356861, 2012). "Caveolin-1 was initially hypothesized to be a tumor suppressor in breast cancer." (PMID 22093547, 2011). "For example, CAV1, down-regulated in the cancer samples, was found to inhibit breast cancer growth and metastasis; the down-regulation of PPARG is associated with local recurrence and metastasis in breast cancer; and ANGPTL4 may act as a regulator of angiogenesis." (PMID 21060876, 2010). "However, several lines of evidence have suggested that Cav-1 may have oncogenic properties leading to breast cancer." (PMID 18811984, 2008). "In addition, our study found that breast cancer patients with tumours that expressed low levels of CAV1 mRNA tended to have larger tumour sizes, which supported the hypothesis that CAV1 acts as a growth suppressor in breast tumours." (PMID 15305200, 2004).
breast carcinoma (continued). "Clinical database analysis of the cBioPortal and UALCAN platforms further revealed that breast cancer and TNBC patients have lower levels of CAV1 protein." (PMID 40192514, 2025). "Breast cancer cells trigger oxidative stress in CAFs and activate two autophagic driving factors, namely HIF-1 α and NF- κ B, leading to autophagic degradation of Cav-1 in CAFs." (PMID 41030451, 2025). "17β-estradiol (E2) can induce tumor cell growth by promoting the activation of the high mobility group box 1 protein (HMGB1)/Cav-1 pathway, enhancing autophagy and inhibiting apoptosis in BT474 human breast cancer cells." (PMID 41030451, 2025). "According to one study in breast cancer patients, based on the expression of specific markers CD29, FAP, FSP1, α-SMA, CAV-1 and dipeptidylpeptidase 4 (DPP-4, CD26), CAFs can be classified into four subtypes: CAFs-S1 to S4." (PMID 40940764, 2025). "In breast cancer cell lines, P4 can increase the complex formation of SHP2-caveolin-1, which prevented the P4-increased formations of Csk-p-caveolin-1 and Csk-cSrc) complex, hence increasing the phosphorylation of cSrcY416 and causing cSrc activation." (PMID 39996064, 2025). "Herein, we investigate the role of CAV1 gene expression in relation to PAM50 subtypes, ROR scores, and their joint impact on clinical outcome in two large breast cancer cohorts." (PMID 38509243, 2024). "In breast cancer, CAF markers such as FAP, α-SMA, Vimentin, FSP1, PDGFRα, PDGFRβ, Caveolin-1, and PDPN have been validated." (PMID 39519118, 2024). "(B) KM plotter analysis of EHD2, CAV1 and CAV2 overexpression correlation with relapse-free survival (RFS) for upper vs. lower quartiles in basal-like breast cancer (PAM50-based) cohorts of TCGA, GEO, and GEA datasets." (PMID 36625722, 2023). "Downregulation of Cav-1 can decrease the activity of ATP-binding box family G protein subfamily 2 (ABCG2) in BCRP and improve the chemotherapy sensitivity of drug-resistant breast cancer cells." (PMID 37828916, 2023). "In the treatment of breast cancer, the uptake of certain drugs, such as albumin-paclitaxel and trastuzumab-metan conjugate (T-DM1), depends on Cav-1-mediated selective endocytosis." (PMID 37828916, 2023). "In inflammatory breast cancer (IBC) cells, the high expression of Cav-1 activates the Akt1 signaling pathway and phosphorylates the RhoC-GTP enzyme, thereby promoting the adhesion and migration of breast cancer cells and enhancing cell invasion." (PMID 37828916, 2023). "Strikingly, the expression levels of Caveolin 1 in MDA-MB-231 were higher compared to the other cell lines, suggesting for this breast cancer clone a high rate of caveolae-mediated endocytosis." (PMID 36986886, 2023). "Conversely, other works have reported that upregulation of CAV1 in TME promotes invasion and metastasis at a later stage in breast cancer development." (PMID 35660849, 2022). "The expression of CAV1 was reported to mediate endocytosis and promote the internalization of T-DM1 into HER2-positive breast-cancer cells, thereby triggering apoptosis." (PMID 35158857, 2022). "Since we reported the downregulation of CEMMs and enhanced autophagy level were observed in human breast cancer cells and tissues, here we further analyzed the expression of CEMM marker protein CAV1 in both normal and tumor tissues from TCGA database." (PMID 34786475, 2021). "Further investigations revealed that ursolic acid suppressed breast cancer growth and lung metastasis by impairing glycolytic metabolism via inducing the SP1/Cav-1 pathway." (PMID 34568078, 2021). "Shear stress-induced Caveolin-1 activation can induce PI3K/AKT/mTOR signaling and metalloprotease activity, which have been shown to promote cell motility and metastasis of breast carcinoma cells." (PMID 33718218, 2021).